HOXA9 (homeobox A9)
Diseases named in the same sentence as HOXA9 in open-access papers (continued):
Sharing a sentence is not in itself a finding about the gene and the disease.
ovarian carcinoma (continued). "Overexpression of HOXA9 was seen in epithelial ovarian cancers." (PMID 28969042, 2017). "In addition, the module contains a DM mark adjacent to HOXA9 that was reported to be significantly hypermethylated in ovarian cancer patients." (PMID 22863767, 2012). "The overall risk of ovarian cancer was increased 12.3 folds by high HOXA9 methylation for all stages and 14.8 folds for early-stage ovarian cancers, independent of age, phase of the menstrual cycle, and histology of the cancer." (PMID 20145720, 2009). "However, recent studies have shown that HOXA9 expression increases considerably in advanced stages of ovarian cancer, indicating that it may have a different function as the disease progresses." (PMID 20219106, 2010). "As such, methylation analysis of genes like HOXA9 and HIC1 in conjunction with cancer antigen 125 levels are reported to offer efficient and effective surveillance of ovarian cancer." (PMID 41301911, 2025). "The homeobox A9 (HOXA9) and hypermethylated cancer-1 (HIC1) promoter methylation in serum cell-free DNA samples showed an AUC of 0.95 in discrimination between ovarian cancer and healthy controls." (PMID 38275400, 2024). "CDR1as also promotes the resistance of NSCLC to cisplatin through miR-641/Homeobox Protein Hox-A9 (HOXA9) pathway, while in ovarian cancer it shows the opposite effect through the miR-1270/Suppressor of Cancer Cell Invasion (SCAI) signal pathway." (PMID 35205613, 2022). "Herein, the promoter methylation of seven ovarian cancer-specific genes (RASSF1A, DAPK1, SOX1, HOXA9, HIC1, SPARC, and SFRP1) was analyzed quantitatively in 120 tissue samples by MethyLight assay." (PMID 34778370, 2021). "Methylation of HOXA9 was found positive in 80.0% (16/20) patients with stage I/II cancer, 81.5% (44/54) of stage III, and 90.9% (10/11) of stage IV ovarian cancer patients." (PMID 34778370, 2021). "Simultaneous methylation of SOX1+HOXA9 exhibited positivity for methylation in 75.0% (15/20) of stage I/II, 85.2% (46/54) of stage III, and 81.8% (9/11) of stage IV of ovarian cancer." (PMID 34778370, 2021). "The homeobox transcription factor genes HOXA7, HOXA9, HOXA10, and HOXA11 have an important role in the morphologic heterogeneity of epithelial ovarian cancers and their assumption of mullerian-like features." (PMID 20145720, 2009). "APC, CDH13, CRABP1, HOXA9, HOXB5, RASSF1A, and SCGB3A1 were found to be hypermethylated both in the primary tumours and in ovarian cancer cell lines, whereas ADAMTS1 and MGMT were hypermethylated only among cell lines." (PMID 17623056, 2007). "CDH13, CRABP1, HOXA9, and SCGB3A1 were subjected to direct bisulphite sequencing in the four ovarian carcinoma cell lines." (PMID 17623056, 2007). "In ovarian cancers specifically, CAFs can induce angiogenesis through the secretion of IL-6, COX-2, and CXCL1, while ovarian cancer cells are reported to induce CAFs to secrete CXCL12, IL-6, and VEGF-A expression via HOXA9, leading to angiogenesis." (PMID 36672620, 2023). "Similarly, the two-gene panel of SOX1 + HOXA9 was found positive for methylation in 80.0% (8/10) of stage I/II, 56.7% (17/30) of stage III, and 80.0% (4/5) of stage IV ovarian cancers." (PMID 34778370, 2021). "Methylated HOXA9, HIC1, and SOX1 exhibited a similar trend to identify ovarian cancer at various stages of disease in 70.0% (7/10) patients with stage I/II cancer, 56.7% (17/30), 70.0% (21/30), and 43.3% (13/30) of stage III, respectively and 80.0% (4/5) of stage IV ovarian cancer patients." (PMID 34778370, 2021). "The combined panel of HOXA9 + HIC1 and HIC1 + SOX1 exhibited the best discriminatory efficiencies at all stages of ovarian cancer (100.0% (10/10) of stage I/II, 80.0% (24/30) and 70.0% (21/30) of stage III, respectively and 80.0% (4/5) and 100.0% (5/5) of stage IV of ovarian cancer, respectively)." (PMID 34778370, 2021).
ovarian carcinoma (continued). "The aberrantly expressed Hoxa9 in patients with epithelial ovarian cancer has no significant predictive value during first-line platinum-taxane chemotherapy." (PMID 33402862, 2020). "The study found that in the patients with ovarian cancer, the normal endometrial tissue showed hypermethylation of HOXA9 and HOXA11 but this was not the case in patients without cancer." (PMID 31382546, 2019). "The peak incidence of ovarian cancer is over 60 years, and aging can therefore not be excluded as a contributor to HOXA9 hypermethylation in this disease." (PMID 17623056, 2007). "The investigated gene promoters were chosen from loci previously reported to be methylated in ovarian cancer (n = 7; APC, CDH13, MGMT, MLH1, p14ARF, p16INK4a, RASSF1A) and from loci methylated in other tumour types (n = 6; ADAMTS1, CRABP1, HOXA9, HOXB5, NR3C1, SCGB3A1)." (PMID 17623056, 2007). "In addition, our findings showed that the methylation levels of candidate genes (HIC1, HOXA9, SOX1, DAPK1, RASSF1A, SFRP1, and SPARC) were significantly elevated in patients with ovarian cancer and was highly cancer-specific, which is in concord with the previously published reports." (PMID 34778370, 2021).
breast cancer (43 papers, 2010 to 2025). A primary or metastatic malignant neoplasm involving the breast. "HOXA9 was found to be downregulated in breast cancers, and reduced HOXA9 expression was linked to the malignant phenotype of breast tumor." (PMID 36376832, 2022). "Four of the ten closest genes with probes available showed moderate association with breast cancer survival at P < 0.005 (HOXA9, HOTTIP, EVX1 and TAX1BP1), with these associations mainly observed for ER-negative breast cancer." (PMID 30787463, 2019). "Using the survival data, we examined the association between the survival rate of breast cancer patients after surgery and the DNA methylation of each of the six CpGs on the HOXA9 and HOXA10 promoters." (PMID 28748001, 2017). "Herein we demonstrated that HOXA9 expression was induced in lrECM 3D culture of the Claudin-low breast cancer cells over conventional 2D culture and such induction was associated with epigenetic activation of the HOXA9 promoter." (PMID 27409175, 2016). "Their study identified homeobox A9 (HOXA9) as a gene frequently down regulated in human breast cancers, and noted that reduced HOXA9 transcript levels are associated with tumor aggression, metastasis, and patient mortality." (PMID 26132924, 2015). "A similar cooperative relationship between the polycomb repressors, Ezh2, Suppressor of Zeste12, and DNA methyltransferases has been shown in HOXA9 gene silencing upon loss of p16INK4a tumor suppressor activity in breast cancer cells." (PMID 20814569, 2010). "HOXA9 Functions as a transcription factor and is linked to proliferation, invasion, and metastasis of solid tumors such as colon cancer, nasopharyngeal carcinoma and breast carcinoma." (PMID 39462379, 2024). "In breast cancer, HOXA9 overexpression activates signaling along the WNT pathway and is associated with a poor prognosis." (PMID 35743243, 2022). "Triple-negative breast cancer (TNBC) is a highly invasive subtype of breast cancer, HOXA9 was reported to be regulated by LncRNA MIR503HG in TNBC through miR-224-5p." (PMID 36376832, 2022). "In this study, miR-638 was found to suppress the tumorigenesis of breast cancer through targeting HOXA9 and suppressing Wnt/β-cadherin pathway." (PMID 34416888, 2021). "According to these findings, HOXA9 was considered to participate in the pathogenesis and prognosis of breast cancer." (PMID 34416888, 2021). "In a word, miR-638 can directly bind to HOXA9 and negatively regulate HOXA9 expression in breast cancer." (PMID 34416888, 2021). "IHC showed that positive detection of HOXA9 protein expression was in the nucleus of breast cancer cells." (PMID 34416888, 2021). "Previous research showed that HOXA9 had oncogenic functions in hematologic cancers and anticancer effects in breast cancer and NSCLC." (PMID 31906958, 2020). "On the other hand, as a tumor suppressor, HOXA9 inhibits the tumor phenotype by regulating the expression of BRCA1 in breast cancer." (PMID 31013831, 2019). "It has been also reported that Stratifin (SFN) is methylated in 96% of breast cancer patients, whereas Homeobox A9 (HOXA9) and Engrailed homeobox 1 (EN1) are methylated in 95% and 80% of serum patients with ovarian tumor, respectively." (PMID 31443448, 2019). "In breast cancer, HOXA9 and its downstream target BRCA1 are significantly downregulated, which was thought to be critical for the development of breast cancer in patients lacking estrogen receptor/progesterone receptor expression." (PMID 29662084, 2018). "Among the up-regulated HOX genes in lrECM 3D culture we chose to focus on HOXA9 because of its robust induction in lrECM 3D culture and its critical roles in breast cancer." (PMID 27409175, 2016). "In summary we demonstrate that HOXA9 expression is activated by binding of BRD4 to the CpG hypomethylated HOXA9 promoter in the Claudin-low breast cancer cells attached to ECM." (PMID 27409175, 2016). "In the Luminal breast cancer cells HOXA9 suppresses tumor progression via activation of PTEN expression." (PMID 27409175, 2016).
breast cancer (continued). "In breast cancer, HOXA9 was reported to regulate the expression of the tumor suppressor BRCA1, and re-expression of HOXA9 led to reduced proliferation and migration of malignant cells." (PMID 27598218, 2016). "HOXA9 expression is repressed by increased stiffness in the Luminal breast cancer cells via miR-18's targeting of HOXA9." (PMID 27409175, 2016). "Restoring HOXA9 expression repressed growth and survival and inhibited the malignant phenotype of breast cancer cells in culture and in a xenograft mouse model." (PMID 26132924, 2015). "In breast cancer cells, HOXA9 has been shown to directly regulate BRCA1 expression and to suppress growth and survival." (PMID 24886209, 2014). "The tumor suppressor function of HOXA9 has been extensively investigated in breast cancer where it has been shown that HOXA9 directly regulates BRCA1 and a number of other genes involved in invasion, growth and metastasis." (PMID 24886209, 2014). "Subsequent to TET1 gene expression, TET1 auto-demethylates its promoter and, subsequently, the demethylation of the promoter of homeobox A (HOXA) genes, HOXA7 and HOXA9, culminating in the effect from the TET1, HOXA7, and HOXA9 genes suppressing breast cancer invasion and metastasis." (PMID 38994941, 2024). "Consequently, HOXA9 expression enhances H3K4me3 demethylation, which culminates in the stemness of breast cancer cells by suppressing cellular differentiation." (PMID 38994941, 2024). "Elevated HOXA9 expression has also been observed in breast cancer." (PMID 38285101, 2024). "Opposing study found that HOXA9 blocked breast cancer progression through BRCA1 modulation." (PMID 39462379, 2024). "In addition, HOXA9 showed reduced expressions in breast cancer and its inhibition prevented cell growth." (PMID 39462379, 2024). "Furthermore, miR-638 directly binds to HOXA9 in breast cancer, and miR-638 impeded breast cancer progression through targeting HOXA9." (PMID 34416888, 2021). "Next, HOXA9 expression was identified in breast cancer tissues." (PMID 34416888, 2021). "Furthermore, miR-638 can directly bind to HOXA9, and increased expression of HOXA9 was also detected in breast cancer." (PMID 34416888, 2021). "Moreover, miR-638 inhibited breast cancer progression via targeting HOXA9 and suppressing EMT/Wnt/β-cadherin pathway." (PMID 34416888, 2021). "miR-638 inhibits breast cancer progression through binding to HOXA9." (PMID 34416888, 2021). "In current research, we also found the upregulation of HOXA9 in breast cancer." (PMID 34416888, 2021). "Therefore, this study suggested that miR-638 served as a tumor inhibitor to impede the malignant progression of breast cancer via suppressing the expression of HOXA9 and activation of Wnt/β-cadherin pathway." (PMID 34416888, 2021). "HOXA9 overexpression has been correlated to a less invasive behaviour of breast cancer cells." (PMID 33375038, 2020). "The expression of TET1 or HOXA9 significantly reduced the bone metastasis of breast cancer cells." (PMID 31013831, 2019). "In breast cancer, stiff matrix is found to be associated with poor survival and tumor aggressiveness, probably due to the activation of MYC and the suppression of phosphatase and tensin homolog (PTEN) and homeobox A9 (HOXA9)." (PMID 30934860, 2019). "While HOXA9 and other HOX genes have been shown to be transcriptionally regulated by HOTAIR in fibroblasts and breast cancer cell lines, it is currently unknown whether a similar regulation of HOXA9 may also occur in glioma." (PMID 29644006, 2018). "In this study, we show that a combination of HOXA9 and HOXA10 promoter methylation markers is significantly associated with the prognosis of breast cancer patients in independent datasets and compose a transcriptional regulation module through long-range chromatin interactions." (PMID 28748001, 2017). "Both TET1 and HOXA9 suppressed breast cancer development in nude mice." (PMID 28780773, 2017). "In breast cancer, HOXA9 and HOXA10 act as tumor suppressor genes." (PMID 28748001, 2017).
breast cancer (continued). "We speculate that HOXA9's tumor suppressive activity is neutralized by other concurrently induced tumor-promoting HOX genes in lrECM 3D culture of the Claudin-low breast cancer cells." (PMID 27409175, 2016). "It would be interesting to investigate, whether the restoration of GDF3 level in breast cancer would increase HOXA9 expression and thereby reduce malignancy of disease and improve the clinical outcome for the patient." (PMID 23950971, 2013). "In early-stage breast cancer patients, low levels of TET1 mRNA were associated with poor survival rates, and in breast cancer cell line and mouse xenograft models, TET1 was reported to regulate tumor growth and metastasis by demethylating HOXA7 and HOXA9 promoter regions." (PMID 36979633, 2023). "Furthermore, breast cancer patients with high HOXA9 expression had shorter overall survival." (PMID 34416888, 2021). "Moreover, the upregulation of HOXA9 was detected in breast cancer tissues." (PMID 34416888, 2021). "In brief, miR-638 was speculated to impede breast cancer progression by targeting HOXA9." (PMID 34416888, 2021). "However, HOXA9 was significantly downregulated in breast cancers relative to normal breast tissues." (PMID 28969042, 2017). "Sun et al32 discovered the high mobility group AT-hook 2 (HMGA2)–TET1–homeobox A9 (HOXA9) pathway, establishing it as a prognostic marker for breast cancer survival." (PMID 40520993, 2025). "For example, in breast cancer, TET1 can demethylate its own promoter and the promoter of HOXA genes, enhancing its own expression and stimulating HOXA7 and HOXA9 expression." (PMID 33375038, 2020). "In breast cancer, when HMGA2 is depleted, an induction of the TET1 and HOXA9 genes occurs inhibiting invasion and metastization." (PMID 33375038, 2020). "The combination of long-range interacting HOXA9 and HOXA10 promoter CpGs predicted the survival of breast cancer patients, providing a comprehensive and novel approach for discovering new methylation markers." (PMID 28748001, 2017). "We suggest that the promoter-promoter interaction between HOXA9 and HOXA10 is important in breast cancer progression through the enhancer-like action of HOXA10 promoter CpGs." (PMID 28748001, 2017). "To assess the value of the combination of the HOXA9 and HOXA10 promoter CpG methylation markers as a prognostic marker for breast cancer, we performed a multivariate Cox proportional hazards analysis with other subtype markers." (PMID 28748001, 2017). "In particular, alternatively spliced variants of PRMT2 were related to survival and the invasiveness of breast cancer cells, while high expression of RARG and HOXA9 has been observed in human hepatocellular carcinomas and acute leukemia." (PMID 24401680, 2014). "Among the genes amplified in the focal regions were a cluster of HOX genes (HOXA7, HOXA9, HOXA10, HOXA11) on 7p15, AKT1 (14q32.33), IGF1R (15q26.3), ERBB2 and NEUROD2 (17q12), all of which have been reported in primary breast cancers." (PMID 24489661, 2014). "It has previously been reported that HOXA9, a paralog of HOXA10, is a tumor suppressor in breast cancer, and expression of HOXD10 in MDA-MB-231 significantly impaired migration." (PMID 22439757, 2012). "We developed a multiplex digital droplet polymerase chain reaction (ddPCR) assay for the detection of ctDNA in breast cancer patients that targets a combination of two methylations specific for breast tissue (LMX1B and ZNF296) and one cancer specific methylation (HOXA9)." (PMID 37225860, 2023). "Finally, intersecting specific DMGs of the two patients, we observed common tumor pathways involved in lymphoma and breast cancer including transcription factors and oncogenes (e.g., FOXD3/ESR1/HOXA9/BCL11B)." (PMID 37029309, 2023). "TET1 positively modulated HOXA9 by directly binding to or inducing the histone binding of H3K4Me3 to the HOXA gene promoter regions, leading to local demethylation and gene transcription in breast cancer." (PMID 34957093, 2021).
breast cancer (continued). "In particular, HOXA9 upregulation can impair anti-tumor effect of miR-638 in breast cancer, and miR-638 can hinder the Wnt/β-cadherin pathway and epithelial-mesenchymal transition (EMT) in breast cancer." (PMID 34416888, 2021). "Furthermore, HMGA2 depletion in breast cancer cells resulted in downregulation of miR-29 and induction of its target TET1, which in turn demethylates the promoter of the metastasis-suppressor HOXA9 and promotes its transcription." (PMID 30149591, 2018). "Thus, we suggest that the long-range interplay of HOXA9 and HOXA10 promoter CpGs is an efficient and robust methylation marker for breast cancer." (PMID 28748001, 2017). "HOXA9 and HOXA10 have been reported to be tumor suppressor genes in breast cancer." (PMID 28748001, 2017). "Thus, we suggest that the combination of HOXA9 and HOXA10 methylation markers is an independent prognostic marker for breast cancer." (PMID 28748001, 2017). "Therefore, we suggest that the prognostic model using the HOXA9 and HOXA10 promoter CpG combination has translational potential to facilitate determination of breast cancer prognosis and therapeutic strategies targeting a specific molecular regulation module." (PMID 28748001, 2017). "Also, as a tumor suppressor, miR-429 could inhibit the activation of the Wnt/β-catenin signaling pathway by targeting HOXA9 in osteosarcoma and FN1 in breast cancer." (PMID 38002073, 2023). "In addition, it has been reported that the combination of HOXA9 and HOXA10 promoter CpG islands could predict the survival of breast cancer patients." (PMID 33634306, 2021). "Moreover, HOXA9 expression was found to have negative correlation with miR-638 in breast cancer tissues (R2 = 0.4964)." (PMID 34416888, 2021). "However, the functions of Wnt/β-catenin pathway and HOXA9 were not reported in breast cancer." (PMID 34416888, 2021). "By performing 3C PCR assays in MCF7 and MDA-MB-231 breast cancer cells and MCF10A normal breast cells, we confirmed that the HOXA9 and HOXA10 promoters physically interacted each other, while the HOXA11 promoter did not interact with the HOXA9 or HOXA10 promoter." (PMID 28748001, 2017).